MIR4442 (microRNA 4442)
Synonyms: hsa-mir-4442; mir-4442
Gene: MicroRNA gene on chromosome 3 (25,664,873 to 25,664,939, reverse strand). Ensembl gene ENSG00000283971.
Homologues: Orthologues: chimpanzee MIR4442 (100% identical).